INS (insulin)
Diseases named in the same sentence as INS in open-access papers (continued):
Sharing a sentence is not in itself a finding about the gene and the disease.
type 2 diabetes (continued). "Recent evidence suggests that environmental temperature may have beneficial effects on insulin sensitivity and type 2 diabetes." (PMID 32359193, 2020). "This study tested the hypothesis that serine protease plays a pivotal role in type 2 diabetes, and inhibition of serine protease activity prevents hyperglycemia in diabetic animals by modulating insulin signaling pathway." (PMID 32015418, 2020). "Some individuals are not obese on the basis of height and weight, are insulin-resistant, predisposed to type 2 diabetes, and have premature coronary heart disease." (PMID 32819267, 2020). "Results in previous one-way or two-way MR analyses showed nonsignificant association between type 2 diabetes or fasting insulin with Alzheimer’s disease, but were not consistent for fasting glucose." (PMID 33202379, 2020). "For instance, we detected BRCA1 in Breast Cancer, Amyloid Precursor Protein (APP) in Alzheimer’s Disease, INS in A1C measurement and Type 2 Diabetes, PCSK9 in LDL cholesterol levels and SNCAIP in Parkinson’s Disease, and the circadian rhythm gene CRY2 in Morning vs. Evening chronotype." (PMID 32678846, 2020). "Since AMPK can be activated pharmacologically to improve glucose and lipid metabolism in insulin-resistant mice, it could be a promising new target for treating type 2 diabetes." (PMID 33142995, 2020). "Unlike patients with shorter duration type 2 diabetes where weight loss is associated with decreases in fasting plasma insulin, we found no overall difference in fasting or postprandial plasma C-peptide or circulating GLP-1 at 12 months." (PMID 32049634, 2020). "Male Wistar rats, fed with a high-fat diet and treated with a low dose of STZ (30–40 mg/ kg body weight) is reported to be a reliable model for human type 2 diabetes symptoms, which include peripheral insulin resistance, increased plasma interleukin-6 (IL-6) and hyperglycemia." (PMID 32282828, 2020). "Notably, autophagy abnormality has been recently associated with metabolic disorders, such as type 2 diabetes, and the BECN1 protein was shown to regulate insulin secretion." (PMID 32804959, 2020). "These aspects are important to understand for situations in which a rapid or sustained delivery of glucose to the circulation and tissues is required (e.g., sports nutrition or compensation of insulin dosage-induced hypoglycemia in diabetes patients), or generally to be avoided (type 2 diabetes)." (PMID 32733909, 2020). "SCGN might play a different role in insulin secretion in patients with type 2 diabetes than in pregnancy and women with gestational diabetes." (PMID 32708966, 2020). "Oral administration of the extract of T. cordifolia roots for two weeks experimented with induced type 2 diabetic rats resulted in this plant can promote insulin secretion and inhibit glucosgenolysis process and therefore improve the regulation of blood glucose level in the body." (PMID 32872226, 2020). "Type 2 diabetes (T2D) is a metabolic disorder characterized by insulin resistance which may also be combined with insufficient amount of insulin release from pancreatic β-cells." (PMID 32419826, 2020). "Although inflammation and metabolic dysfunction of β-cells elicit secretory defects associated with type-1 or type-2 diabetes, accompanying changes to insulin granules have not been established." (PMID 33164744, 2020). "First, researchers observed some nodal and paranodal abnormalities that were unique to insulin- and c-peptide-deficient T1D and did not occur in hyperinsulinemic and c-peptide-abundant type 2 diabetes (T2D)." (PMID 33419247, 2020). "Indeed, the level of ci-INS was found to be significantly lower in the islets of type 2 diabetes donors and to be inversely correlated to HbA1c levels." (PMID 33154349, 2020). "Increased nuclear retention of PTBP1 in the islets of individuals with type 2 diabetes may also contribute to impaired glucose-stimulated insulin biosynthesis." (PMID 32894308, 2020).
type 2 diabetes (continued). "Exogenous insulin supplementation may reduce concentrations of CCL5 in patients with newly diagnosed type 2 diabetes compared with the control subjects." (PMID 32194402, 2020). "Of these, 127 600 participants with type 2 diabetes initiating insulin therapy were included in the main study cohort (mean [SD] age, 59.4 [12.6] years; 68 588 men [53.8%] and 59 012 women [46.2%]), with 108 672 (85.2%) in the HI group and 18 928 (14.8%) in the AI group." (PMID 31977057, 2020). "In contrast, the Sorensen model allows the simulation of normal subjects, of type 2 Diabetes patients who still maintain some level of endogenous insulin secretion, and of Type I Diabetes patients for which endogenous insulin production is completely replaced by external inputs." (PMID 32797106, 2020). "These remarkable features, combined with the well-known possibility to breakdown almost 80% of the insulin-stimulated glucose uptake, make the skeletal muscle a specialized tissue to manage insulin sensitivity and, whenever defective, a primary player in type 2 diabetes pathogenesis." (PMID 32528404, 2020). "We tested the hypothesis that family history of type 2 diabetes (FHD) is associated with reduced birth weight and reduced insulin secretion later in life." (PMID 33490284, 2020). "Furthermore, for type 2 diabetes patients initially treated with insulin, introducing liraglutide had a beneficial effect on GV estimated by CGM." (PMID 32622354, 2020). "Interestingly, human islets derived from type 2 diabetes individuals exhibited attenuated circadian oscillations, paralleled with reduced insulin and glucagon exocytosis." (PMID 33374803, 2020). "This activation is reported to result in increased insulin secretion in mouse under normal conditions but not in glucolipotoxicity thus causing dysregulated TAAR signalling in type 2 diabetes." (PMID 33488196, 2020). "Various light-activation modes applied to opto-IR1 expressing diabetic mice could aid in understanding of the nature of insulin resistance and help to optimize schedules of insulin injection in diabetes type II patients." (PMID 33209247, 2020). "Adiponectin, with its insulin-sensitizing, antiatherogenic, antiapoptotic, and antiinflammatory effects, may play a role in future therapies for obesity, type 2 diabetes, and atherosclerosis." (PMID 31905496, 2020). "The impairments of endothelial insulin NO production may importantly contribute to the development of vascular injury in hypertension, obesity, and type II diabetes." (PMID 32851077, 2020). "The key question is whether glucose disposal in people with prediabetes or type 2 diabetes is limited exclusively by impairment in insulin-dependent GLUT4 translocation or insulin-dependent tissue perfusion." (PMID 32595948, 2020). "Interestingly, the thioredoxin interacting protein (TXNIP), which inhibits the antioxidative action of thioredoxin and is elevated upon ER stress and insulin misfolding, was also found to be elevated in type 2 diabetes islets." (PMID 32894308, 2020). "Furthermore, n-3 PUFA supplementation in type 2 diabetes patients brought leptin levels down and increased the adiponectin level, which resulted in positive effects on lipid profile, insulin, and glycosylated hemoglobin." (PMID 32059381, 2020). "However, 11 of the stroke participants had known type 2 diabetes and were currently being treated (seven on metformin, glyburide or both; three on some form of insulin injection; one on a DPP4 inhibitor)." (PMID 33375333, 2020). "The goal of this study was to determine whether rosiglitazone (RSG), a drug used to improve insulin sensitivity in type 2 diabetes, could enhance insulin transport at the BBB, as a potential therapeutic for improving memory." (PMID 32704569, 2020).
type 2 diabetes (continued). "The biguanide metformin has been studied in the context of exercise capacity, quality of life and mood states, and metabolic adaptations, such as insulin production and clearance, oxidative stress and cardiometabolic health in older adults with prediabetes and Type II diabetes." (PMID 33071237, 2020). "On the other hand, for patients with type 2 diabetes, some methods including short duration intensive insulin therapy and reduction of body weight by intensive lifestyle interventions could be adopted to reverse diabetes." (PMID 32901098, 2020). "Insulin secretion has been widely investigated in obesity and type 2 diabetes." (PMID 32860984, 2020). "Automated insulin delivery (artificial pancreas systems) and also digitally enhanced technologies for multiple-daily insulin administration, such as smart pens in combination with continuous glucose monitoring, are arising as cost-effective solutions in type 2 diabetes management." (PMID 33198734, 2020). "Type 2 diabetes (T2D) is a chronic metabolic disorder that has reached epidemic proportion throughout the world and this disease is characterized by a defect in the secretion of insulin and resistance to insulin in its target organs." (PMID 32156083, 2020). "Insulin secretion from β-cells is reduced at the onset of type-1 and during type-2 diabetes." (PMID 33164744, 2020). "Our observations that SR141716A evoked insulin release at 2 mM glucose are in agreement with the requirement for some rimonabant-treated patients to reduce their anti-diabetic medication, and induction of hypoglycaemic episodes by rimonabant in some insulin-treated patients with type 2 diabetes." (PMID 31925452, 2020). "However, impairment of insulin secretion is a more important pathophysiological condition in type 1 diabetic and Asian type 2 diabetic patients." (PMID 33244056, 2020). "After 30 days of treatment, B. vernae extract significantly decreased the serum levels of fasting blood glucose, insulin, insulin resistance index, glycated serum protein, TNF-α, IL-1β, and IL-6, whereas significantly increased the serum levels of insulin sensitivity index in type 2 diabetic rats." (PMID 32636751, 2020). "In this population-based cohort, elevated C-peptide levels are associated with an increased risk of type 2 diabetes independent of glucose, insulin levels, and clinical risk factors." (PMID 32957570, 2020). "Metformin is the first-line drug in type 2 diabetes mainly by improving insulin sensitivity." (PMID 32467714, 2020). "Contrary to type 1 diabetes which is due to a severe decrease in insulin secretion by the pancreas, type 2 diabetes is due to defects in signal transduction between the insulin receptor and the molecular mechanisms involved in glucose uptake and other metabolic actions of insulin." (PMID 33665204, 2020). "Advanced age, insulin treatment, type 2 diabetes, presence of hypertension and low peripheral saturation were strongly associated with risk of hospitalization, and might require specific management." (PMID 33233575, 2020). "Premixed insulin and basal insulin plus short-acting insulin regimens may be of value for treating individuals with type 2 diabetes (T2DM) who are fasting during Ramadan due to simplicity and better compliance." (PMID 33425548, 2020). "In addition, Kv7.1 channels in the pancreatic ß-cells contribute to the regulation of insulin secretion, and loss of function mutations in the KCNQ1 gene leads to impaired ß-cell insulin secretion, which is associated with type 2 diabetes." (PMID 32695022, 2020). "Furthermore, in type 2 diabetic Goto-Kakizaki rats, which were characterised by changes in blood glucose and insulin, Glut2 was reduced, and changes in its distribution patterns were evident." (PMID 32365865, 2020).
type 2 diabetes (continued). "Novel bifunctional molecules described in this review build on this anti-inflammatory action and will have the capacity to impact multiple factors including blood pressure, lipid and triglyceride levels, and insulin signaling in metabolic diseases like MetS, type 2 diabetes and NAFLD." (PMID 33776749, 2020). "Thus, the recovered pancreatic cells and restored insulin sensitivity are important mechanisms of the EtOAc extract to treat type 2 diabetes." (PMID 33489029, 2020). "In contrast, some studies have shown increased insulin secretion due to an HP diet and have even suggested that an HP diet could be beneficial in case of type 2 diabetes." (PMID 31991777, 2020). "The resulting downregulation of the insulin signaling cascade prevents the translocation of glucose transporter to the plasma membrane and glucose uptake into skeletal muscle, leading to metabolic disorders such as type 2 diabetes." (PMID 32178449, 2020). "Excessive insulin signaling through the insulin receptor (IR) may play a role in the pathogenesis of diet-induced metabolic disease, including obesity and type 2 diabetes." (PMID 32350271, 2020). "In addition, iron regulates iron reduction, insulin secretion, endothelial dysfunction, and metabolic control in people with type 2 diabetes." (PMID 32280714, 2020). "Insulin-induced hypoglycemia is prevalent in type 1 diabetes and advanced type 2 diabetes." (PMID 33042003, 2020). "Then, secondly, could insulin-induced CB overactivation be a predictor of type 2 diabetes development?" (PMID 32698380, 2020). "However, people with type 2 diabetes are treated with diet, hypoglycemic agents, or insulin depending on their glycemic control, other aspects of the management of the disease and the presence of complications." (PMID 31906543, 2020). "Given the association of disturbances in non-esterified fatty acid (NEFA) metabolism with the development of Type 2 Diabetes and Non-Alcoholic Fatty Liver Disease, computational models of glucose-insulin dynamics have been extended to account for the interplay with NEFA." (PMID 31581241, 2019). "While both types of exercise generally increase insulin sensitivity in older adults, the metabolic pathways through which this occurs can differ and can be dependent on preexisting conditions including obesity and type 2 diabetes." (PMID 31684154, 2019). "In a rat model of type 2 diabetes, treatment with adropin could increase insulin sensitivity and reduce blood glucose level and insulin resistance." (PMID 31781629, 2019). "In type 2 diabetes, the origin of beta cell malfunctioning is diverse and mainly attributed to a systemic low-grade inflammation which also impairs the various organs ability to make use of insulin and remove glucose from the blood." (PMID 30863457, 2019). "It is therefore possible that compensatory effects due to type 2 diabetes may hyperactivate insulin signaling in certain brain regions where insulin signaling was originally less affected, thus aggravating AD." (PMID 30652125, 2019). "After the identification of the improving effect of JQJT tablets on the gut barrier, since insulin resistance was closely related to the low level inflammatory response in type 2 diabetes we evaluated the effect of JQJT tablets on inflammation by checking the levels of IL-6, TNF-α, and MCP-1." (PMID 30733971, 2019). "Based on the data of glucose dynamics measured by CGM, we analyzed complexity and fractality of a pregnant woman with type 2 diabetes that was treated successfully with continuous subcutaneous insulin infusion and CGM, and compared the results in two treatment periods." (PMID 31595155, 2019). "So this new peptide from the gut had potential to influence blood glucose in two ways, both by stimulating glucose-induced insulin release and by inhibiting glucagon secretion, both of which would limit hepatic glucose production, the main driver of the fasting hyperglycemia of type 2 diabetes." (PMID 31080438, 2019).
type 2 diabetes (continued). "Our results implicate that GLP-1 analogues could be an effective treatment option for South Asian patients with type 2 diabetes, possibly through improving insulin sensitivity via a specific reduction in visceral adipose tissue." (PMID 31288820, 2019). "Patients with type 2 diabetes were predominantly treated with non-insulin drugs." (PMID 30778899, 2019). "Then, recombinant strains carrying insulin were administered to type II diabetes mellitus mice." (PMID 30744426, 2019). "Our observations support the clinical notion that adherence to basic treatment recommendations is indispensable in type 2 diabetes care if metabolic and clinical treatment goals are to be met, and if inappropriate add-on over-medicalization with OADs and/or insulin is to be avoided." (PMID 31830073, 2019). "Type 2 diabetes mellitus (T2DM) is one of the most prevalent metabolic diseases worldwide and characterized by hyperglycemia accompanied by progressive and irreversible loss of pancreatic insulin secretion." (PMID 32082162, 2019). "It has been discovered that BMP7, one of the gene ontology annotations in GO kidney mesenchyme development, could augment insulin sensitivity in mice with type 2 diabetes by potentiating PI3K/AKT pathway." (PMID 31407623, 2019). "Type 2 diabetes (T2D) is characterized by worsening pancreatic β‐cell function often requiring treatment escalation with oral antidiabetic drugs (OADs), glucagon‐like peptide‐1 and eventually insulin." (PMID 31294087, 2019). "Thus, EVOO intake regulated glucose homeostasis by improving insulin sensitivity and pancreatic β-cell function, in a type 2 diabetes HFD animal model." (PMID 31383924, 2019). "Physiologically, after nutrient stimulation, the insulin:amylin molar ratio in peripheral circulation is approximately 10-100:1; however, in diabetic conditions, amylin concentration decreases (type 1 diabetes) or its production is impaired (type 2 diabetes)." (PMID 31428627, 2019). "In the development of type 2 diabetes, it is currently recognized that insulin resistance occurs in prediabetic state that shows hyperinsulinemia due to the compensation for reduced insulin sensitivity." (PMID 30478982, 2019). "The effect of some insulin-sensitizing molecules could be related to the increased mitochondrial content, as type 2 diabetes features are related to lower mitochondria presence." (PMID 30863477, 2019). "In contrast, it is still a matter of debate whether the impaired autocrine factors such as autocrine insulin signaling participate in type 2 diabetes development." (PMID 30450940, 2019). "A study in human subjects also demonstrated a blunted insulin-mediated decrease in plasma FFA levels after insulin clamp in patients with type 2 diabetes compared to healthy, normoglycemic, or obese individuals, thus supporting the clinical significance of the observed effects in this study." (PMID 31920980, 2019). "In the past decade, a plethora of disease relevant genetic loci have been identified by genetic association studies (e.g. GWAS) of clinically phenotyped populations for metabolic diseases/traits including Type 2 Diabetes, waist-to-hip ratio, body mass index and fasting insulin." (PMID 30940487, 2019). "Indeed, studies in animals and humans with type 2 diabetes showed that oral administration of DCAs (sebacic acid) improved glycemic control, probably by enhancing insulin sensitivity, and reduced hepatic gluconeogenesis and glucose output." (PMID 31293078, 2019). "A lower incidence of NAFLD has been found in patients with type 1 diabetes compared to patients with type 2 diabetes, and it is suggested that insulin treatment’s inhibiting effect on lipolysis is responsible for the decreased level of free fatty acids accumulating in the liver." (PMID 30943987, 2019). "However, by the 1950s it was recognized that a subset of people with type 2 diabetes were less responsive to insulin and this was accompanied with being overweight or obese." (PMID 31263701, 2019).